ACSF3 (acyl-CoA synthetase family member 3)
Description:
Catalyzes the initial reaction in intramitochondrial fatty acid synthesis, by activating malonate and methylmalonate, but not acetate, into their respective CoA thioester. May have some preference toward very-long-chain substrates.
Tractability: PROTAC: ubiquitination databases record sites on it; its protein half-life has been measured.
Target class: Enzyme; Ligase
Gene: Protein-coding gene on chromosome 16 (89,088,375 to 89,164,121, forward strand). Ensembl gene ENSG00000176715.
Subcellular location: Mitochondrion
Subcellular location (Human Protein Atlas): Mitochondria
Pathways (Reactome):
Metabolism: Synthesis of very long-chain fatty acyl-CoAs
Gene Ontology:
Molecular function: malonyl-CoA synthetase activity; protein binding; very long-chain fatty acid-CoA ligase activity
Biological process: fatty acid biosynthetic process; fatty acid metabolic process; malonate catabolic process; long-chain fatty-acyl-CoA biosynthetic process
Cellular component: mitochondrion; mitochondrial matrix
Genetic constraint (gnomAD): Loss-of-function variants: 81 observed, 56.77 expected, observed/expected ratio (o/e) 1.43, 90% interval 1.19 to 1.72. The synonymous counts are far from expectation, so gnomAD's model fits this gene poorly and the ratio says little. Missense variants: 932 observed, 779.04 expected, observed/expected ratio (o/e) 1.2, 90% interval 1.13 to 1.26. Synonymous variants: 414 observed, 337.36 expected, observed/expected ratio (o/e) 1.23, 90% interval 1.13 to 1.33.
Gene-disease validity (ClinGen):
ClinGen rates the evidence that ACSF3 causes each of these diseases.
combined malonic and methylmalonic acidemia (autosomal recessive): Definitive. Combined malonic and methylmalonic acidemia is a rare inborn error of metabolism characterized by elevation of malonic acid (MA) and methylmalonic acid (MMA) in body fluids, with higher levels of MMA than MA.
Homologues: Orthologues: chimpanzee ACSF3 (98% identical), macaque ACSF3 (90% identical), rat Acsf3 (80% identical), pig ACSF3 (80% identical), mouse Acsf3 (79% identical), guinea pig ACSF3 (77% identical), dog ACSF3 (75% identical), tropical clawed frog acsf3 (60% identical), zebrafish ACSF3 (58% identical), Drosophila melanogaster Acsf3 (28% identical), Caenorhabditis elegans acs-21 (27% identical), Caenorhabditis elegans acs-11 (26% identical). Paralogues in human: ACSF2 (22% identical), ACSS2 (21% identical), ACSM4 (21% identical), ACSM5 (20% identical), ACSM3 (20% identical), AASDH (20% identical), ACSS1 (20% identical), ACSM1 (19% identical), ACSM2A (18% identical), ACSM2B (18% identical), ACSS3 (16% identical), AACS (14% identical), and 1 more.
Diseases named in the same sentence as ACSF3 in open-access papers:
ACSF3 is named in the same sentence as 28 diseases in open-access papers, as found by Europe PMC text mining. Sharing a sentence is not in itself a finding about the gene and the disease. The quoted sentences say what the papers report.
rheumatoid arthritis (2 papers, 2021 to 2023). A chronic, systemic autoimmune disorder characterized by inflammation in the synovial membranes and articular surfaces. "ACSF3 is differentially expressed in ligament and may influence risk of rheumatoid arthritis." (PMID 37884875, 2023).
alcoholic liver diseases (1 paper, 2021). A disorder caused by damage to the liver parenchyma due to alcohol consumption. "Studies have shown that ACSF3 is significantly up-regulated in the process of alcoholic liver disease, participates in fatty acid and lipid metabolism, and accelerates liver damage." (PMID 35071379, 2021).
Hypertension (1 paper, 2016). The presence of chronic increased pressure in the systemic arterial system. "Notably, SUMF1, F2R and IQGAP2 (found in the case group) and ACSF3 (found in the control group) identified in the initial study were replicated in the replication cohort, suggesting potential role of these genes in pathophysiology of hypertension related LVH." (PMID 26930585, 2016).
Intellectual disability (1 paper, 2020). "Additional proteins included AAAS, ACSF3, and ADSSL1, which are known to be associated with neurodevelopmental abnormalities that present with intellectual disability and impaired learning and memory." (PMID 32850779, 2020).
lung carcinoma (1 paper, 2021). "Interestingly, a high level of acyl-coA synthetase family member 3 (ACSL3) was observed in human lung cancer, and the enzyme was found to play an essential role in the tumorigenesis of lung cancers bearing KRAS G13D mutation." (PMID 33466836, 2021).
methylmalonic acidemia (1 paper, 2023). A genetically heterogenous inherited disorder characterized by abnormalities in the metabolism of lipids and proteins. "Moreover, young patients with mutations affecting the ACSF3 gene, diagnosed with combined malonic and methylmalonic acidemia via newborn screening, may present no clinical symptoms or signs indicative of a metabolic disorder at a young age." (PMID 37160609, 2023).
non-alcoholic fatty liver disease (1 paper, 2022). "Recent report emphasized that pharmacological activation of the SIRT3/ACSF3 pathway was an effective approach to alleviate NAFLD and protocatechuic acid was a novel candidate therapy for non-alcoholic fatty liver disease." (PMID 36205594, 2022).
short chain acyl-CoA dehydrogenase deficiency (1 paper, 2018). "In some cases ACSF3 defects only cause biochemical conditions such as short-chain acyl-CoA dehydrogenase deficiency or 3-methylcrotonylglycinuria, and symptoms appear only during viral infections etc.." (PMID 30041674, 2018).
steatosis (1 paper, 2023). Increased lipid within the cytoplasm of cells. "Although it also has antioxidant and anti-inflammatory properties, PCA bound and upregulated the SIRT3 protein to prevent liver damage and steatosis in HFD-fed mice, likely by regulating the acetylation and degradation of Acyl-CoA synthetase family member 3 (ACSF3) and fatty acid metabolism." (PMID 37834101, 2023).
very long chain acyl-CoA dehydrogenase deficiency (1 paper, 2021). An inherited disorder of mitochondrial long-chain fatty acid oxidation with a variable presentation including: cardiomyopathy, hypoketotic hypoglycemia, liver disease, exercise intolerance and rhabdomyolysis. "In this study, we focus on two diseases of mitochondrial fatty acid metabolism, i.e., very long-chain acyl-CoA dehydrogenase deficiency (VLCADD) and malonyl-CoA synthetase deficiency (acyl-CoA synthetase family member 3 (ACSF3) deficiency)." (PMID 33917608, 2021). "We focus specifically on two diseases: very long-chain acyl-CoA dehydrogenase deficiency (VLCADD) and malonyl-CoA synthetase deficiency (acyl-CoA synthetase family member 3 (ACSF3)) deficiency, which are both characterized by alterations in metabolic flexibility." (PMID 33917608, 2021).
metabolic disease (4 papers, 2021 to 2023). A congenital disorder (due to inherited enzyme abnormality) or acquired (due to failure of a metabolically important organ) disorder resulting from an abnormal metabolic process. "In human metabolic diseases research, ACSF3 as a cause of combined malonic and methylmalonic aciduria (CMAMMA) has been studied." (PMID 35071379, 2021). "ACSF3 deficiency was the first human disorder identified and caused human metabolic disorders." (PMID 36980926, 2023).
ACSF3 also shares sentences with these, for which no sentence is quoted: and methylmalonic aciduria (2 papers); cancer (2); systemic lupus erythematosus (2); autism spectrum disorder (1); breast carcinoma (1); butyrylcholinesterase deficiency (1); depression (1); Ehlers-Danlos syndrome (1); hearing loss (1); infection (1); liver disease (1); Parkinson ́s disease (1); pontocerebellar hypoplasia (1); primary immunodeficiency (1); propionic acidemia (1); spastic paraplegia type 7 (1); viral infections (1).